CCND1 (cyclin D1)
Diseases named in the same sentence as CCND1 in open-access papers (continued):
Sharing a sentence is not in itself a finding about the gene and the disease.
prostate carcinoma (continued). "A pioneering study evidences the importance of Cyclin D1 as a crucial regulator of tumor-stroma interactions, in prostate cancer progression." (PMID 33317149, 2020). "Cyclin D1 classified as a pro oncogene is often over-expressed in several human malignancies including breast, colon, lung and prostate cancers." (PMID 32807213, 2020). "MAP30 reduced expression of the self-renewal Wnt pathway effector molecule β-Catenin and its target genes c-Myc and cyclin D1 in glioma and prostate cancer cells." (PMID 32726914, 2020). "Previous studies have shown that TGF‐β1 inhibits Cyclin D1 in prostate cancer and other cancer types, in order to constrain prostate cancer growth and metastatic progression." (PMID 33174391, 2020). "Overexpression of HNF1B in prostate cancer cells led to the arrest of G1 cell cycle and decreased Cyclin D1 expression." (PMID 33174391, 2020). "Knockdown of BMI1 in docetaxel resistant prostate cancer cells inhibited the expression of cyclin D1 or BCL2, the downstream targets of the Wnt/β–catenin pathway." (PMID 32726929, 2020). "Cyclin D1 is a key regulator of cell cycle, which promotes cell proliferation and is amplified or overexpressed in several types of human cancer, including prostate cancer." (PMID 33174391, 2020). "This study showed that adjacent normal tissues had higher CCND1 expression in than prostate cancer tissues in mRNA and cytoplasmic protein level, and perhaps due to nucleo-cytoplasmic transport, nuclear CCND1 showed opposite distribution characteristic." (PMID 32566661, 2020). "The compound inhibited the activity of PIN1, to stabilize cyclin D1, which improved anti-proliferative effects of prostate cancer treatment through new mechanisms." (PMID 32258027, 2020). "For example, lncRNA SNHG7 facilitates prostate cancer carcinogenesis via cyclin D1 by sponging miR-503." (PMID 32781986, 2020). "To further confirm the correlation between HNF1B and Cyclin D1 expression in prostate cancer samples, we first analysed online publicly available data sets from TCGA data set and GSE21032." (PMID 33174391, 2020). "Together, downregulation of RORα1 and upregulation of cyclin D1, c-myc, and c-jun were observed in prostate carcinoma tissues as well as in cancer cells." (PMID 30987323, 2019). "Metformin has been demonstrated to inhibit the growth of cancer cells through inducing G1-phase arrest by reducing the cyclin D1 level in prostate cancer cells." (PMID 30754729, 2019). "This work identified transforming growth factor-β (TGF-β) and cyclin D1 (CCND1) as putative mediators of resistance as confirmed in preclinical models of prostate cancer." (PMID 31013891, 2019). "Apigenin reduced the level of cyclin D1, followed by cell cycle arrest in the G0/G1 phase in LNCaP and PC-3 prostate cancer cell lines." (PMID 30823649, 2019). "Ellagic acid or ellagitanins from pomegranate juice also inhibited proliferation of prostate cancer cells by inhibiting the expression of cyclin D1 and cyclin B1, and triggered the intrinsic and extrinsic apoptosis pathways." (PMID 31835645, 2019). "Reduction of cyclin D1 expression is also found in nasopharyngeal cancer (C666-1), prostate cancer (LNCaP) and head and neck squamous cell carcinoma (FaDU and Detroit 562) incubated with 5-20 mM metformin for 72 h." (PMID 31244286, 2019). "Immunohistochemistry experiments revealed a low expression of cyclin D1, c-myc, and c-jun in normal prostate tissues, and an upregulation of cyclin D1, c-myc, and c-jun in prostate carcinoma tissues." (PMID 30987323, 2019). "Alpha- and γ-tocopherol, as well as their final metabolites α- and γ-CEHC, suppressed cyclin D1 expression and inhibited PC-3 prostate cancer cell proliferation." (PMID 31340453, 2019). "Some clinical study has confirmed that overexpression of CCND1 (Cyclin D1) is a common biomarker for treatment and being ignored to cisplatin resistance in prostate cancer." (PMID 30867653, 2019).
prostate carcinoma (continued). "To further investigate the molecular mechanism underlying cell cycle arrest, we examined the effect of TA treatment on cell cycle regulatory proteins (cell cycle inhibitory proteins (p21INK4C and p18INK4C) and cyclin D1) in prostate cancer cells." (PMID 29518944, 2018). "Classified as an oncogene, cyclin D1 is often over-expressed in a number of human malignances including colon, breast, lung and prostate carcinomas." (PMID 30108509, 2018). "CXCL8 enhanced resistance to anoikis in colorectal cancer cells, promoted castration-resistant through PI3K/AKT/mTOR pathway and regulating cyclin D1 in prostate cancer cells." (PMID 30723697, 2018). "Our study provides additional evidence that top-60 miRNAs are involved in Prostate Cancer Signaling, in particular, through the modulation of Ras, P ten and Cyclin D1 genes." (PMID 29740090, 2018). "Studies with other ETS proteins, such as ETS-2, have shown that a similar down-regulation of cyclin D1 occurs upon ETS-2 reduction in prostate cancer cells, resulting in growth inhibition." (PMID 29050229, 2017). "This study found that PlncRNA-1 acts as a cancer gene in prostate cancer, and it can regulate the cell cycle and Cyclin-D1." (PMID 28212533, 2017). "In our study, knockdown of ESM1 showed up-regulation of cyclin D1 and down-regulation of p21 with the results of increased proliferation of prostate cancer cells." (PMID 28108731, 2017). "In prostate cancer cells, cytoplasmic cyclin D1/CDK4 complexes phosphorylate paxillin, a structural component of focal adhesions." (PMID 29066743, 2017). "Nuclear localization of ALK5-ICD also promotes its own expression by binding to the TβRI promoter and regulates cell cycle, differentiation, and invasiveness in prostate cancer through cyclin D1 (CCND1)." (PMID 27166254, 2016). "Analysis of prostate cancer from TCGA data demonstrated a significant positive correlation between expression of Slug and that of cyclin D1 and c-Jun." (PMID 27385093, 2016). "Together, these results suggest that TMPRSS4 induces prostate cancer cell proliferation through upregulation of cyclin D1." (PMID 27385093, 2016). "Despite the evidence collected implicating cyclin D1 in DNA repair and radioresistance of cancer cells, little is known about its role in prostate cancer cells and the relationship between cyclin D1, androgen independency and radioresistance." (PMID 26689991, 2016). "In previous studies Ccnd1 gene deletion was associated with reduced proliferation of prostate epithelial cells and induction of a cyclin D1 mediated gene signature that predicted poor outcome and recurrence free survival in prostate cancer patients." (PMID 26689991, 2016). "In this study, we report that TMPRSS4 induces Slug and cyclin D1 through AP-1 activation in PC3 prostate cancer cells, leading to both invasion and proliferation." (PMID 27385093, 2016). "Taken together, these results suggest that TMPRSS4 induces AP-1 activation and subsequent induction of Slug and cyclin D1, leading to prostate cancer cell invasion and proliferation." (PMID 27385093, 2016). "Using data from The Cancer Genome Atlas, we found that Slug expression positively correlated with that of c-Jun and cyclin D1 in human prostate cancers." (PMID 27385093, 2016). "In this study, we found that TMPRSS4 induced AP-1 activation and subsequent expression of Slug and cyclin D1, leading to prostate cancer cell invasion and proliferation." (PMID 27385093, 2016). "miR-16 is decreased in prostate cancer, whereas the expression levels of its targets, namely Bcl-2, CCND1 and WNT3A, are inversely increased." (PMID 26655091, 2016). "We showed that the expressions of miR-193b and CCND1 are inversely correlated in prostate cancer cell lines and xenografts." (PMID 26129688, 2015).
prostate carcinoma (continued). "In the present work, nitroxoline induced a dramatic down-regulation of cyclin D1 expression and inhibition of Rb phosphorylation that explained the G1 arrest of cell cycle and indicated the potential against prostate cancers." (PMID 26447757, 2015). "It is known to negatively regulate cyclin D1 and loss of ATF3 was recently shown to promote prostate cancer in a transgenic mouse model." (PMID 26304929, 2015). "In conclusions, we have demonstrated that the overexpression of cyclin D1 in prostate cancer is driven, at least partly, by the reduced expression of miR-193b." (PMID 26129688, 2015). "To assess the relevance of cyclin D1 targeting by miR-193b in prostate cancer cells, we studied the activity of the cyclinD1–RB pathway in the regulation of the G1/S transition in the cell cycle." (PMID 26129688, 2015). "Immunohistochemical analysis of cyclin D1 showed that castration-resistant prostate cancers have significantly (P = 0.0237) higher expression of cyclin D1 compared to hormone-naïve cases." (PMID 26129688, 2015). "To confirm that miR-193b binds to the 3’UTR -region of the CCND1 gene in prostate cancer cells, we performed a luciferase reporter assay." (PMID 26129688, 2015). "In prostate cancer, cyclin D1 has been shown to function as a corepressor to androgen receptor (AR) 18–20." (PMID 26129688, 2015). "Using a reporter assay, we confirmed that miR-193b targets the 3’UTR of the CCND1 gene in 22Rv1 prostate cancer cells." (PMID 26129688, 2015). "Additional support for this conclusion comes from the finding that cyclin D1 overexpression in LNCaP prostate cancer cells increased the fraction of S-phase cells and decreased growth factor requirements for their proliferation." (PMID 26372468, 2015). "It was reported that α-mangostin for 24 h suppressed cyclin-D1 which was followed by apoptosis in prostate cancer cells." (PMID 24812621, 2014). "Similar to the silencing of CDC25A, reevesioside A induced a profound down-regulation of CDC25A, cyclin D1 and cyclin E, facilitating G1 arrest of the cell cycle in prostate cancers." (PMID 24475272, 2014). "The CCND1 gene is overexpressed in several types of human cancers and an increased expression of cyclin D1 in the prostate cancer cell line enhanced cell growth and tumorigenicity." (PMID 24858012, 2014). "Both survivin and cyclin D1 were down-regulated in the two cell lines as they are in prostate cancer cell lines by a different ART derivative." (PMID 23516601, 2013). "Cyclin D1 expression significantly decreased following Rac1/Cdc42 inhibition in prostate cancer cells." (PMID 24040362, 2013). "Previous studies have shown the ability of NF-kB to promote cell growth and proliferation of prostate cancer cells via various mechanisms, including regulation of c-myc, cyclin D1, Bcl-2 and IL-6." (PMID 24062781, 2013). "The four miRNAs regulate PTEN expression post-transcriptionally, and affect the downstream PI3K/Akt pathway via PIK3CA (p110α), PIK3CD (p110δ), PIK3R1 (p85), Akt as well as cyclin D1, thus promote prostate cancer cell proliferation in vitro." (PMID 24098737, 2013). "In prostate cancer cells, metformin treatment led to a dose-dependent inhibition of proliferation through a decrease in cyclin D1 levels, correlated with blocking cell cycle in the G0/G1 phases." (PMID 24351837, 2013). "Overexpression of Cyclin D1 has also been reported to increase tumorigenicity of the LNCaP prostate cancer cell line." (PMID 24040362, 2013). "Taken together, our results demonstrate that SUMO modification of ATF3 influences CCND1/2 activity and cellular proliferation of prostate cancer PC3 and DU145 cells and explains at least in part how ATF3 functions to regulate cancer development." (PMID 23591848, 2013). "The antitumor activity of EF24 also appears to reflect a direct effect of EF24 on prostate cancer cell proliferation as the expression of both cyclin D1 and Ki67 was markedly reduced in tumor xenografts from EF24-treated mice." (PMID 23940701, 2013).
prostate carcinoma (continued). "For example, in the LNCaP prostate cancer cells, curcumin represses total β-cat level, as well as GSK-3 phosphorylation, associated with reduced c-Myc and cyclin D1 expression." (PMID 22253696, 2012). "Pc-3 (prostate cancer cells) treated with gum mastic of P. lentiscus showed cyclin D1 downregulation and G1 block of the cell cycle." (PMID 23351343, 2012). "In support, we define Cyclin D1 as another direct target suppressed by miR-449a in prostate cancer cells." (PMID 20948989, 2010). "Mining of publicly available human prostate cancer oligoarray datasets revealed that the expression of numerous genes (e.g., CCND1, CD44) under the control of β-catenin transcription is down-regulated." (PMID 20454608, 2010). "Treatment of PC-3-M prostate cancer cells with 10 μM Lovastatin for 36 h induced cyclin D1 degradation." (PMID 17407548, 2007). "It has been previously shown through in vitro studies that cyclin D1 can influence androgen-dependent prostate cancer cell proliferation through its dual ability to modulate both CDK4 and AR activity." (PMID 17375037, 2007). "Cyclin D1 is a critical regulator of androgen-dependent transcription and cell cycle progression in prostate cancer cells." (PMID 17375037, 2007). "Despite the importance of cyclin D1 in eliciting and modulating the androgen response in prostate cancer, few studies have examined the expression profile of this protein in localised tumours or evaluated its relevance for disease progression." (PMID 17375037, 2007). "Cyclin D1 has the potential to regulate both cellular proliferation and AR-dependent transcription in prostate cancer cells." (PMID 17375037, 2007). "Using this inclusive approach, 63% of tumours and only 8% of normal epithelia scored positive for cyclin D1, indicating that the protein is accumulated in prostate cancer." (PMID 17375037, 2007). "Our data indicate that this process, in part, is likely to be responsible for the disparate localisation of cyclin D1 in prostate cancer." (PMID 17375037, 2007). "Despite the influence of D-type cyclins on prostate cancer proliferation, few studies have examined the expression of cyclin D1 in localised tumours or challenged its relevance to disease progression." (PMID 17375037, 2007). "Recent studies in prostate cancer model systems have shown that cyclin D1 accumulates after androgen stimulation as a result of mTOR activation and resultant enhancement of cyclin D1 mRNA translation." (PMID 17375037, 2007). "Together, these studies associated differential expression and localisation of cyclin D1 with important clinicopathological parameters and suggest new insight concerning the potential consequence of cyclin D1 induction in prostate cancer." (PMID 17375037, 2007). "In prostate cancer cells, it has been shown that cyclin D1 induction is insufficient to drive androgen-independent proliferation, and forced elevation of cyclin D1 in the presence of androgen suppresses rather than promotes cellular proliferation." (PMID 17375037, 2007). "The repressor functions occur at stoichiometric levels of AR and cyclin D1, thus indicating that modest elevations of cyclin D1 can have significant effects on prostate cancer growth." (PMID 16863592, 2006). "The most striking disparity in function between the two cyclin D1 proteins in the context of prostate cancer was observed using cellular proliferation as an endpoint." (PMID 16863592, 2006). "The rationale for combining CDK4/6 inhibitors with radiation is in part based on data supporting the importance of cyclin D1 in radio-sensitizing prostate cancers and the possibility that CDK4/6 inhibition may potentiate the effects of radiation." (PMID 40075623, 2025). "Our study demonstrated slightly lower cyclin D1 expression in prostate cancer compared to BPH." (PMID 41465498, 2025).
prostate carcinoma (continued). "These factors are essential, as Cyclin D1 is pivotal for cell cycle regulation, while Bcl-2 plays a crucial role in promoting cell survival, thus highlighting the importance of aberrant AR signaling in the pathology of prostate cancer." (PMID 40008000, 2025). "Furthermore, in prostate cancer, the expression of cyclin D1 appears to increase the capacity for tumor invasion, reinforcing the involvement of this protein in the more aggressive behavior of some tumors." (PMID 38742684, 2024). "Conversely, downstream factors of the Wnt pathway, including β-catenin, TCF/LEF transcription factors, and target genes like c-myc and cyclin D1, participate in malignant phenotypes such as cell proliferation, anti-apoptosis, angiogenesis, and metastasis in prostate cancer." (PMID 38994113, 2024). "Previous studies searching for inhibitors in the atypical NFκB signaling pathways identified a specific inhibitor of androgen receptor and p52 interaction resulting in reduced levels of cyclin D1 expression used for the treatment of castration-resistant prostate cancer." (PMID 38238702, 2024). "Similarly, we demonstrated that cyclin D1 expression was significantly reduced following MA treatment compared to the control group in all the tested prostate cancer cell lines." (PMID 38605607, 2024). "CCND1 was over‐expressed in more aggressive prostate cancer phenotypes, and its expression was regulated by oestrogens via ERβ and might contribute to the progression and pathogenesis of prostate cancer." (PMID 37378426, 2023). "Besides the role of cyclin D1 in the DNA repairing processes in some cell types, this cyclin unequivocally supports cell proliferation of prostate cancer cells." (PMID 37284895, 2023). "In this study, for the first time, we demonstrated that RASAL2 was upregulated in prostate cancer and associated with the cell cycle, tumour growth and poor disease prognosis, in which the PI3K/AKT signalling pathway and cyclin D1 expression played an important role." (PMID 35668070, 2022). "Interestingly, prostate cancer cells express low levels of this miRNA and high levels of cyclin D1, supporting tumor progression." (PMID 36498861, 2022). "Collectively, these results indicated that PSMC2 may promote the development of prostate cancer by regulating the Akt/Cyclin D1/CDK6 pathway." (PMID 33902600, 2021). "LncRNA LOXL1-AS1 modulates miR-541-3p/CCND1 pathway to promote prostate cancer growth and invasion." (PMID 33589577, 2021). "In addition, a miR-425-5p mimic suppresses the expression of cyclin D1 and targets GSK3β, to increase the sensitivity of prostate cancer cells to cisplatin." (PMID 33406670, 2021). "The GSEA plots in a Metastatic Prostate Cancer dataset from cBioportal showed that SIRT6 was positively correlated with the cell cycle-related gene Cyclin D1, indicating SIRT6 may promote prostate cancer proliferation." (PMID 33995674, 2021). "Furthermore, our group also demonstrated that ORAI1 silencing is responsible for cell-cycle blockade due to decreased expression of cyclin D1 in prostate cancer cell lines." (PMID 34831241, 2021). "Moreover, the involvement of PSMC2 in prostate cancer was mediated by the activity of Akt/Cyclin D1/CDK6 signaling pathway." (PMID 33902600, 2021). "Our experimental data might provide a strategy for targeting with the PSMC2/Akt/Cyclin D1/CDK6 signalling pathway interaction as a novel therapeutic application to treat prostate cancer patients." (PMID 33902600, 2021). "Besides, dose-dependent inhibition of proliferation via a reduction in cyclin D1 levels arresting in the G0/G1 stage was observed in gastric and prostate cancer cells." (PMID 33350292, 2021). "In addition, we alleviated HNF1B‐mediated cell growth inhibition of prostate cancer cells by overexpression of Cyclin D1 both in vitro and in vivo." (PMID 33174391, 2020). "LOXL1-AS1 contributes to prostate cancer cell growth by regulating miR-541-3p/CCND1 axis." (PMID 33061856, 2020).